CHAD (chondroadherin)
Description:
Promotes attachment of chondrocytes, fibroblasts, and osteoblasts. This binding is mediated (at least for chondrocytes and fibroblasts) by the integrin alpha(2)beta(1). May play an important role in the regulation of chondrocyte growth and proliferation (By similarity).
Synonyms: SLRR4A
Tractability: Antibody: UniProt places it where antibodies can reach, with medium confidence; UniProt predicts a signal peptide or a membrane-spanning region; its Gene Ontology location is reachable by antibodies, with medium confidence.
Gene: Protein-coding gene on chromosome 17 (50,464,496 to 50,468,976, reverse strand). Ensembl gene ENSG00000136457.
Subcellular location: Secreted, extracellular space, extracellular matrix
Gene Ontology:
Molecular function: protein binding; signaling receptor activity
Cellular component: gel phase of interstitial matrix; plasma membrane
Genetic constraint (gnomAD): Loss-of-function variants: 18 observed, 25.35 expected, observed/expected ratio (o/e) 0.71, 90% interval 0.49 to 1.05. The upper end of that interval is the gene's LOEUF score, 1.05, which puts it in group 4 of 6, group 1 being the genes least tolerant of losing a copy. Missense variants: 440 observed, 489.33 expected, observed/expected ratio (o/e) 0.9, 90% interval 0.83 to 0.97. Synonymous variants: 195 observed, 223.28 expected, observed/expected ratio (o/e) 0.87, 90% interval 0.78 to 0.98.
Homologues: Orthologues: chimpanzee CHAD (99% identical), macaque CHAD (98% identical), dog CHAD (97% identical), pig CHAD (96% identical), guinea pig CHAD (94% identical), mouse Chad (93% identical), rat Chad (93% identical), Caenorhabditis elegans sma-10 (18% identical), Drosophila melanogaster CG7509 (18% identical), Drosophila melanogaster CG18095 (17% identical), Drosophila melanogaster Con (15% identical), Drosophila melanogaster kek3 (15% identical), and 3 more. Paralogues in human: CHADL (41% identical), LRIG1 (23% identical), TRIL (22% identical), CPN2 (21% identical), LRIG2 (20% identical), LRIG3 (19% identical), LRRC24 (18% identical), LGR6 (17% identical), LRG1 (17% identical), LRRTM2 (17% identical), LGR5 (16% identical), LGR4 (14% identical), and 10 more.
Diseases named in the same sentence as CHAD in open-access papers:
CHAD is named in the same sentence as 23 diseases in open-access papers, as found by Europe PMC text mining. Sharing a sentence is not in itself a finding about the gene and the disease. The quoted sentences say what the papers report.
breast carcinoma (3 papers, 2017 to 2025). "CHAD encodes a chondroadherin and a truncated version termed cyclicCHAD has been shown to inhibit breast cancer cell growth." (PMID 27902461, 2017). "It has previously been associated with prevalent breast cancer, incident COPD, an age-by-sex interaction and the levels of 17 proteins including CRP, SERPING1, CHAD and CGA." (PMID 41361833, 2025). "The presence of the Col1A1/CHAD amplification event in the mouse model mirrors the 25% of human HER2 + ve breast cancers that also had amplification of a structurally conserved region." (PMID 31332182, 2019). "There is similar amplification event at 17q21.33, including COL1A1 and CHAD that occurs in 8% of breast cancer patients." (PMID 31332182, 2019). "To test whether COL1A1 and CHAD were driving the metastasis phenotype in human breast cancer, we used CRISPRi20 to create a pooled population of COL1A1 and CHAD knockdown in the Her2 amplified, COL1A1/CHAD amplified breast cancer line BT-474." (PMID 31332182, 2019).
hepatocellular carcinoma (3 papers, 2017 to 2022). A malignant tumor that arises from hepatocytes. "Low levels of CHAD have been associated with poor survival in hepatocellular carcinoma." (PMID 35281270, 2022). "In conclusion, as a potential prognostic biomarker, tumor suppressor gene CHAD represses migration and proliferation of hepatocellular carcinoma cells, probability via mediating cell-cell adhesion." (PMID 28947969, 2017). "In current work, we found the expression of CHAD (chondroadherin) was significantly reduced in hepatocellular carcinoma compared to the normal tissue, on both mRNA and protein levels, in three independent datasets." (PMID 28947969, 2017). "In summary, CHAD expression alters prognosis of hepatocellular carcinoma may via altering cell adhesion related signaling pathways." (PMID 28947969, 2017). "Thus it is suspect that CHAD also involved in cell-cell interaction in hepatocytes and hepatocellular carcinoma." (PMID 28947969, 2017). "In summary, in current work, we identified a novel prognostic biomarker, CHAD, was down-regulated in hepatocellular carcinoma cells, oppose cell proliferation and migration, predicts a good survival of HCC patients, and may serve as a potential therapy target." (PMID 28947969, 2017). "The expression of CHAD was detected in both hepatocellular carcinoma and normal hepatocytes, suggesting that CHAD may also play some roles in liver cells." (PMID 28947969, 2017).
autoimmune hepatitis (2 papers, 2015 to 2021). Hepatitis caused by autoantibodies. "In this perspective further understanding of the possible pathological role of CHAD protein and presence of its autoantibodies in autoimmune hepatitis should pave the way of new therapies." (PMID 26375394, 2015).
cartilage disease (1 paper, 2020). Softening and degeneration of the CARTILAGE. "An important CHAD paralog is CHADL, which can negatively regulate chondrocyte differentiation, inhibiting cartilage fibrillogenesis and can be used as a marker for cartilage diseases." (PMID 32493207, 2020).
liver fibrosis (1 paper, 2015). "It has been also reported the role of decorin (a SLRP member protein) in extracellular matrix of liver fibrosis as inhibitor of TGF-β, the most powerful profibrotic cytokine, and studies suggest the presence of other SLPR members, such as CHAD, in attenuating TGF-β bioactivity." (PMID 26375394, 2015).
osteoporosis (1 paper, 2022). A condition of reduced bone mass, with decreased cortical thickness and a decrease in the number and size of the trabeculae of cancellous bone (but normal chemical composition), resulting in increased fracture incidence. "In patients with osteoporosis and ovariectomized mice, CHAD was downregulated, thus inhibiting preosteoclast motility and bone resorption." (PMID 36081907, 2022).
sarcopenia (1 paper, 2025). Progressive decline in muscle mass due to aging which results in decreased functional capacity of muscles. "Experimental validation confirmed significant upregulation of USP54, CHAD, and ZDBF2 in aging muscles, and functional analysis revealed enrichment of signaling pathways related to bone development, immune response, and apoptosis, consistent with known mechanisms of sarcopenia." (PMID 41303670, 2025).
cancer (9 papers, 2010 to 2025). A tumor composed of atypical neoplastic, often pleomorphic cells that invade other tissues. "However, reports on other functions of CHAD, including its role during carcinogenesis and cancer development remain limited." (PMID 36860591, 2023). "The results of the present study highlight the role of CHAD in inflammation and cancer invasion." (PMID 36860591, 2023). "However, reports regarding other function of CHAD is still limited, hitherto, including the role of CHAD during carcinogenesis and cancer development." (PMID 28947969, 2017). "In the test data the CHAD gene is clearly hypermethylated in the cancer samples." (PMID 22936948, 2012). "However, few studies have reported the relationship between CHAD expression and cancer development." (PMID 36081907, 2022). "LAMA1, CHAD, ITGA8, and COL11A1 consistently showed hypermethylation in more than half of cancer types; on the contrary, TNN, SPP1, COL6A6, and TNR consistently showed hypomethylation in more than half of types of cancer." (PMID 36311789, 2022). "The roles of CHAD and UGT2A3 in IBD pathogenesis remain less characterized, with CHAD functions primarily established in bone metabolism and cell-cell adhesion, while UGT2A3 research has focused on cancer and drug metabolism, leaving their IBD-specific contributions largely unexplored." (PMID 40821793, 2025).
tumor (6 papers, 2017 to 2025). "In BC, chondroadherin expression has been shown to decrease with increasing tumour malignancy, and its low levels correlate with poorer patient survival." (PMID 41463344, 2025). "Unsurprisingly, the formation of chondroadherin/α2β1 integrin complexes by administering a chondroadherin peptide demonstrated a tumour-suppressor role in BC." (PMID 41463344, 2025). "Positive significant correlations were obtained between the CHAD gene expression levels and mitotic index (p = 0.008; r = 0.476), tumour size (p = 0.029; r = 0.385), and necrosis (p = 0.011; r = 0.455)." (PMID 36860591, 2023). "•Furthermore, there were significant positive correlations between CHAD protein expression levels and tumour size and necrosis." (PMID 36860591, 2023). "Positive significant correlations were obtained between CHAD gene expression and mitotic index (r = 0.476; P = 0.008), tumour size (r = 0.385; P = 0.029) and necrosis (r = 0.455; P = 0.011)." (PMID 36860591, 2023). "There were significant positive correlations between the CHAD protein expression levels and tumour size (p = 0.039; r = 0.360), and necrosis (p = 0.032; r = 0.377)." (PMID 36860591, 2023). "•Positive significant correlations were obtained between CHAD gene expression and mitotic index, tumour size and necrosis." (PMID 36860591, 2023). "In the case of CHAD, its role as a tumor repressor has been described, with reduced levels of expression in hepatocarcinomas that was associated with poor survival and an increased tendency to metastasis." (PMID 34440771, 2021). "The expression of CHAD was significantly enhanced in tumor tissues compared to the (adjacent) normal tissues." (PMID 28947969, 2017). "In this article, we report that another tumor suppressor gene, CHAD, is significantly lowly expressed in tumor tissues than the normal across three independent datasets." (PMID 28947969, 2017). "Furthermore, there were significant positive correlations between CHAD protein expression levels and tumour size (r = 0.360; P = 0.039) and necrosis (r = 0.377; P = 0.032)." (PMID 36860591, 2023). "In addition, the reduction of CHAD expression in tumor cell lines produced an increase in their capacity for migration and proliferation." (PMID 34440771, 2021). "Immunolocalization of CHAD in normal mucosa showed weak expression in absorptive cells and moderate in the stroma, in contrast to weak focal expression in tumor cells, and the analysis of the images showed the differences to be statistically significant (p < 0.001, Wilcoxon test)." (PMID 34440771, 2021). "Furthermore, metastasis-averse HCC and metastasis-incline HCC group comparison, and protein abundance evaluation of normal-tumor-portal vein tumor thrombus pairs indicate that metastatic tendentiousness is reduced along with CHAD abundance." (PMID 28947969, 2017). "Although previous reports mainly highlighted the structural and adhesive roles of chondroadherin in the ECM, more recent findings indicate that its biological influence extends to intracellular signalling mechanisms relevant to tumour progression." (PMID 41463344, 2025). "Expression values of CHAD in normal and cancerous tissues were compared in three independent datasets, including QPCR (N = 67 pairs), TCGA-LIHC (Normal = 50, Tumor = 269) and GEO dataset (GSE77314, N = 50 pairs)." (PMID 28947969, 2017). "We compared the protein abundance in normal-tumor-PVTT pairs, and the result showed that PVTT had a significantly lower level of CHAD than the primary tumor tissues." (PMID 28947969, 2017). "Neither NYX nor PODNL1 mRNA was detected in either tissue type, while around 50% of healthy tissue samples showed variable levels of CHAD transcription, though it was totally absent in tumor tissue." (PMID 34440771, 2021). "In LSCCs, three significant expression alterations that were not detectable in RSCCs were observed specifically PRELP, CHAD and PODN, all of which underwent downregulation in the tumor tissues." (PMID 34440771, 2021).
musculoskeletal disorders (1 paper, 2023). "CHAD could be a possible candidate gene for musculoskeletal disorders." (PMID 40729198, 2023).
CHAD also shares sentences with these, for which no sentence is quoted: aggressive (1 paper); atherosclerosis (1); cervical cancer (1); chronic fatigue syndrome (1); CNS demyelinating disease (1); disc degeneration (1); gastric cancer (1); metastatic disease (1); ovarian carcinoma (1); prostate carcinoma (1); psychiatric disorder (1); sleep-wake disorder (1); vitiligo (1).